TLR7 (toll like receptor 7)
Diseases named in the same sentence as TLR7 in open-access papers (continued):
Sharing a sentence is not in itself a finding about the gene and the disease.
viral infection (continued). "The study thus shows that TLR7 plays a anti-viral role in HBV infection and holds a promising immuno-modulatory therapeutic value against this hepato-tropical viral disease." (PMID 28088184, 2017). "RANK expression was also strongly induced by DCs in mice treated with the TLR7/8 agonist IMQ, indicating that induction of RANK expression on DCs was a direct consequence of viral infection." (PMID 29186688, 2017). "For example, it has been shown that TLR7 ligation induces expression of the cytoplasmic viral RNA-sensing helicase, RIG-I, in order to clear virus infection, thereby linking TLR7 and RIG-I function." (PMID 28928743, 2017). "It is interesting to note that in all three species, TLR7 and TLR9 expression dominates in B cells, indicating an important role in sensing viral infections." (PMID 28890720, 2017). "Initially, we show that multiple cytokines are differentially expressed during viral infection and demonstrate that EV71 infection induces the production of proinflammatory cytokines through regulating TLR7-mediated p38 MAPK, and NF-κB signaling pathways." (PMID 28854257, 2017). "TLR7, MyD88, TRAF6, IRAK4 and NF-κB p65 mRNA were up-regulated after virus infection (p < 0.01) while down-regulated after oseltamivir and FTA treatment (p < 0.01)." (PMID 27128889, 2016). "Thus, in response to TLR7 ligation in the periphery, the brain may specifically produce monocyte and lymphocyte chemoattractants to recruit the appropriate populations required to protect the brain against a potential viral infection." (PMID 27160148, 2016). "This phenotype was mainly related to the activation of intracellular TLRs, including Poly-RIG/TLR3, imiquimod/TLR7, CL097/TLR7/8, and CpG/TLR9; similar events occur during viral infection." (PMID 27286889, 2016). "Interestingly, infection with both viruses markedly promoted the expression of TLR1 and TLR2, which are sensors of bacterial components, which may be explained by the up-regulation of IFNα and IFNγ that could enhance the expression of TLR1, TLR2, TLR3, and TLR7 in viral infections." (PMID 27916934, 2016). "TLR-7 recognizes single-stranded RNA fragments located in endosomes and TLR-7 activation is a common feature of viral infections." (PMID 24624130, 2014). "In fact, it is now known that one of the most effective vaccines, the live-attenuated yellow fever vaccine, activates multiple DC subsets through TLR2, TLR7/8 and TLR9, which leads to a robust balanced immune response." (PMID 26344621, 2014). "TLR7 and TLR8 are involved in the response to viral infections and recognize GU-rich short single-stranded RNA as well as small synthetic molecules such as midazoquinolines and nucleoside analogues." (PMID 23700487, 2013). "These in vivo studies indicated that, after viral infection, the levels of TLR3-4 and especially TLR7-8 were increased in the lungs." (PMID 24039959, 2013). "We found that a TLR7/8 ligand (9.2s) and a combined RIG-I+TLR7-ligand (3p-dsRNA) were able to induce substantial amounts of IFN-α, arguing for a potential efficacy in viral diseases and cancer." (PMID 23940691, 2013). "Endosomal TLR3, TLR7, TLR8, TLR9 are specialized in the sensing of nucleic acids produced notably during viral infections." (PMID 24302927, 2013). "DHA pretreatment also significantly reduced IL-6 and TNF-α pro-inflammatory cytokine production during both TLR-3 and TLR-7 microglia activation, proving that DHA can exert its anti-inflammatory properties in both types of simulated viral infections." (PMID 23398903, 2013). "In this model of viral infection, type 1 IFN production is rapidly induced via a TLR7–dependent process." (PMID 24386204, 2013). "pDCs also express high levels of TLR7 and TLR9 to sense viral infections and mount type 1 interferon responses." (PMID 23055830, 2012). "It is suggested by in vitro studies that HIV viral RNA triggers a TLR7 dependent IFN-α secretion by pDCs leading to a natural response to the viral infection." (PMID 22043290, 2011).
viral infection (continued). "In response to viral infection, pDC further increase IFN production via TLR7 and TLR9 pathways, leading to increased pDC migration and maturation." (PMID 19830165, 2009). "The innate immunity cells also act against viral infections through TLRs including TLR3, TLR7 and TLR8." (PMID 19527497, 2009). "Furthermore, we also explored TLR7-mediated signalling pathways, crucial for the type I interferon (IFN) response (INF alpha (α) and beta (β)) against viral infections." (PMID 40590376, 2025). "In addition, it has been reported that the participation of TLR6, TLR2, and TLR7 actively participates against some viral infections, such as the SARS-CoV-2 virus, which is recognized by TLR2 and subsequently by TLR7 for an effective antiviral response." (PMID 40573281, 2025). "Viral infections, which have been shown to be involved in SLE pathogenesis, promote the exposure of P‐selectin and CD40L (two hallmarks of platelet activation) on platelets via TLR‐7." (PMID 40265572, 2025). "BAY-M2d induced multiple antiviral genes (TLR7, CD74, CES1, HLA-DOA, CD209, and CMPL2), the products of which may be involved in resistance to viral infections." (PMID 40129989, 2025). "TLR7 and TLR8 are two other TLRs that play a role in IFN production in response to viral infection." (PMID 41011507, 2025). "Following viral infection, the activation of TLR3-mediated MyD88-independent signalling and TLR7-mediated MyD88-dependent signalling leads to the activation of the nuclear transcription factor NF-κB, resulting in the upregulation of proinflammatory factor expression." (PMID 39897040, 2025). "Furthermore, the importance of TLRs in viral infections has been underscored by the finding that TLR3, TLR7, and TLR8, along with cytoplasmic RIG-I-like receptors, facilitate the initiation of innate immune responses by recognizing viral nucleic acids." (PMID 38732254, 2024). "The significance of TLRs in viral infections is further highlighted by reports that TLR3, TLR7, and TLR8, along with cytoplasmic retinoic acid-inducible gene I (RIG-I)-like receptors, are instrumental in initiating innate immune responses against viral nucleic acids." (PMID 38732254, 2024). "Martinez Viedma and Pickett studied the behavior of ZIKV infection in human placenta (JEG-3) and human microglia (HMC3) cell lines and found that the TLR7/8 pathway was significantly inhibited in HMC3 cells, whereas it was activated in JEG-3 cells during viral infection." (PMID 38839691, 2024). "The apparent lack of severe viral disease in other known patients is particularly intriguing, as responses to TLR7, TLR8, and TLR9 were abolished in the cells of these patients." (PMID 36880831, 2023). "Predominantly, TLR7, TLR3, and TLR4 are involved in sensing viral infections." (PMID 37515084, 2023). "Like in mammalian, several PRRs exist in chickens, such as TLR3, TLR7, and MDA5, which could also be activated by viral RNA to generate the antiviral immune responses during virus infection." (PMID 36960283, 2023). "The host immune targets such as TLR7, IRF7, IRF5, and IL6, which are involved in the immune response against viral infections, and the sex-specific targets such as AR and ESSR were taken to investigate any possible link with the SARS-CoV-2 host receptors ACE2 and TMPRSS2." (PMID 36992366, 2023). "Moreover, the upregulation of expression of TLR7, MyD88, IRF7, IRAK4, TRAF6, and TRAF3 induced by viral infection were significantly suppressed under FFYH treatment both in vitro and in vivo." (PMID 37089926, 2023). "The virus-infected group of WT and TLR7−/− mice showed weakened activity and delayed response on the second day after virus infection, whereas the mock group did not demonstrate this change." (PMID 35733131, 2022).
viral infection (continued). "Since type I IFN signaling is critical for protection against several viral infections, rASP-1 stands to be a new addition to other known type I IFN stimulating adjuvants such as Poly I:C (TLR3 agonist), R848 (TLR7/8 agonist), CpG (TLR9 agonist) and STING agonists." (PMID 36119026, 2022). "Decreased phosphorylation of IRF7 and TBK-1 in CD14dimCD16+ monocytes, cDC1, and cDC2 from older donors impairs the production of IFN downstream of TLR7/8 and RIG-I pathways in primary antiviral responses and the ability of these cells to respond quickly to viral infection." (PMID 35849213, 2022). "In this study, we were keen to understand the nature of the acute inflammatory response induced by TLR7 activation in the absence of active virus infection." (PMID 34991643, 2022). "Many studies have also shown that viral infection and chronic inflammation induce TLR7 expression in a variety of non-native TLR7-expressing cell types." (PMID 36611736, 2022). "ssRNAs, such as ssRNA40, have been used previously to induce TLR7 signalling for the study of downstream inflammation, however, not in the context of mimicking viral infection." (PMID 34991643, 2022). "During various viral infection, macrophages recognize the PAMP of the influenza virus through the PRR, such as TLR7, RIG-I, and NLR, which initiates intracellular signaling and ultimately secretion of large amounts of proinflammatory cytokines, triggering an irresistible inflammatory storm." (PMID 35722153, 2022). "From these findings we conclude that Siglec-H controls TLR-9-dependent, but not TLR-7 dependent inflammatory responses after virus infections and regulates chemokine responsiveness of pDCs." (PMID 34497606, 2021). "Since B cells primarily express TLR7 and TLR9, we specifically discuss the role of Toll-like receptor (TLR)-mediated B cell responses to viral infections and their role in augmenting adaptive immunity through enhanced cytokine production and antigen presentation." (PMID 34293057, 2021). "Both viral infection and histamine treatment upregulated TLR3 and TLR7 expression." (PMID 34214498, 2021). "With respect to LCMV infection, TLR7 knockout mice (TLR7−/−) are unable to induce type I IFN in high levels in response to the acute LCMV-WE strain (LCMV-WE), which indicates the importance of TLR7 during viral infection." (PMID 33331816, 2021). "In contrast, H1N1 infection did not increase TLR7 expression in the vagal ganglia overall, nor did viral infection induce de novo TLR7 expression in the nerve cell bodies." (PMID 34530852, 2021). "TLR3, TLR7, and TLR8 antagonists can be used against viral infections." (PMID 34425822, 2021). "TLR3, TLR7, TLR8, and TLR9, which recognize double-stranded RNA (dsRNA) (TLR3), single-stranded RNA (ssRNA) (TLR7/8), and CpG DNA (TLR9), are mainly involved in viral infections." (PMID 33123162, 2020). "Up-regulation of TLR7 may results from viral infections such as influenza and this phenomenon is dependent on type I Interferons (IFN) which in turns is produced by TLR7 triggering." (PMID 32774170, 2020). "In the absence of TLR7, both number and functionality of B cells are affected, leading to delayed recovery from virus infection." (PMID 33679702, 2020). "At 12 HPI, TLR7 mRNA was slightly changed in response to GS38 and DK09 viruses infection." (PMID 32046051, 2020). "It demonstrates, following viral infection, the biochemical pathways leading to ROS production, the source of ROS (i.e., NOX2 oxidase), the compartment of ROS production (i.e., endosome), and the subcellular target of ROS (TLR7) that impact antiviral immunity." (PMID 32008365, 2020). "Furthermore, knockdown of TLR7 in CD4 T cells inhibited HIV replication, indicating that this anergic state promotes virus infection." (PMID 33202596, 2020). "This may explain significant dysfunction of CD4+ T cells observed during a chronic viral infection such as HIV, as genomic RNA of the virus constantly triggers TLR7 signaling." (PMID 33297945, 2020).
viral infection (continued). "TLR7 and TLR9 are strongly expressed in plasmacytoid dendritic cells (pDCs), where they are responsible for a high level of IFN-I expression in response to viral infection." (PMID 31178872, 2019). "Our findings not only expand the knowledge about the mechanisms by which TLR7 controls the onset of VSV-induced CNS disease but also indicate the existence of other non-dispensable roles aside of cytokine induction and PRR function in viral infections." (PMID 30930901, 2019). "In conclusion, this study provides support that enhanced responses through TLR7 and −9 may play a role in the induction of a type I IFN signature observed in pSS patients indicating viral infections as potential trigger of the disease." (PMID 30846988, 2019). "The results showed that the expression levels of TLR7, MYD88, IRAK4 and NF-κB were remarkably up-regulated upon viral infection, and Guizhi-and-Mahuang decoction and Yinqiao powder could down-regulate their expressions in wild type mice." (PMID 30151032, 2018). "In this stable cell line, NF-κB activity was enhanced by EV71 infection and R848 stimulation, but attenuated in the presence of shTLR7, shMyD88, shIRAK1, shNF-κB p65, and shNF-κB p50, confirming that TLR7, MyD88, and IRAK1 are involved in the activation of NF-κB during viral infection." (PMID 28854257, 2017). "In addition, the viral infection provoked the activation of several PRRs including TLR3, TLR7, TLR22, MDA5, and LGP2a and b." (PMID 25338079, 2014). "However in PAMs, TLR3, TLR7, and TLR8 mRNA expressions were significantly up-regulated by the viral infection." (PMID 24712747, 2014). "The significance of the induction of TNF-α and IL-6 expression following the TLR7/8-mediated response to ssRNA virus infection is not fully known." (PMID 24191131, 2013). "Circulating pDCs mediate rapid and robust secretion of IFN-α following bacterial or virus infection through TLR7 and TLR9 by sensing either non-methylated DNA or RNA." (PMID 24312342, 2013). "The role of TLR7 in the immune response to CMV has been suggested in a study that used plasmacytoid dendritic cells (PDCs), the main producers of type I IFN in response to viral infection." (PMID 22414065, 2012). "TLR7 and TLR8, located in the endosome, act as anti-viral receptors for recognizing single strand RNA (ssRNA), which is present at various phases of viral infection from viral entry to replication." (PMID 19527497, 2009). "The critical role of SLC15A4-TASL pathway was not restricted to challenge with synthetic agonists, as it was pivotal to control chronic LCMV infection, a viral infection model whose clearance is highly dependent on TLR7, rather than RIG-I-MAVS antiviral response." (PMID 39856058, 2025). "In addition, finding strategies that can manipulate cytokine expression by TLR7-activated pDCs, may also help control certain inflammatory conditions, including SLE, and excessive innate cytokine response during certain viral infections." (PMID 38077311, 2023). "In detail, TLR7 favors the production of cytokines involved in CD4+ T helper 17 (Th17) cell polarization (IL-1β, IL-6, and IL-23) after virus infection with MV and VSV, whereas TLR8 promotes the TH1-promoting cytokine response and type I IFN production after viral infection with ECMV." (PMID 36359340, 2022). "The stimulation of TLR7 with IMQ eventually activated the MDA5 pathway inside the B cells without real viral infection in this model, indicating that the autoimmunity in B cells could be induced by inorganic chemicals in the environment." (PMID 36359746, 2022). "While the connection between TLR7, MAFB, and the IFN response offers an attractive possibility to explain the observed cytokine response, a model where increased MAFB expression because of increased engagement of TLR7 after viral infection raises several issues." (PMID 35065665, 2022).
viral infection (continued). "However, differential roles for the RNA-sensing PRRs during viral infections of the CNS have been identified, most notably for West Nile Virus (WNV), where TLR3, TLR7, and RLR receptors RIG-I and MDA-5 have been shown to coordinate and propagate a protective response." (PMID 35584192, 2022). "To mimic bacterial and viral infections we used a panel of three stimuli (lipopolysaccharide (LPS), resiquimod (R848), and polyinosinic:polycytidylic acid (Poly I:C)) to stimulate the extracellular Toll-like receptor (TLR) 4 and the intracellular TLR7/8 and TLR3, respectively." (PMID 36059528, 2022). "This indicates that the virus infection primes the cells for TLR7 responsiveness, supporting the notion that LCMV may promote cytokine induction from pre-existing M1- and M2-polarized cells." (PMID 33331816, 2021). "Expanding these findings to the autoantigens, viral infection can trigger the onset or progression of autoimmune diseases, as the virus-infected DCs is more potent in the cross-priming of autoreactive CD8+ T cells due to the immunostimulatory effects of viral RNA in TLR7 activation." (PMID 33297945, 2020). "It was shown that HSV-1 could induce TLR7 expression at later phase after virus infection, and the induced TLR7 expression was coincident with the declined expression of TLR3, implicating that TLR3 and TLR7 might act sequentially to response to viral infection and replication in HCECs." (PMID 31889912, 2019). "In contrast, the rs3775290 SNP of TLR3 and TLR7 SNPs were not related to viral infection." (PMID 28046022, 2017). "In recent and elegantly performed studies, activation of platelet TLR7 not only induced platelet-neutrophil aggregation and a reduction in platelet count, but was also necessary for optimal survival in murine models of encephalomyocarditis (EMCV) viral infection." (PMID 25566264, 2014). "Thus, it is plausible that a viral infection might trigger the GCA inflammatory process, or alternatively, TLRs might be activated by endogenous ligands, since some small interfering RNAs may ligate TLR7/8." (PMID 41225346, 2025). "However, unlike patients with impaired IFNAR signaling, patients who are genetically impaired in IFN-I production downstream of TLR7/8/9 signaling do not appear to suffer from life-threatening viral infections, except for respiratory IAV and SARS-CoV-2 infections." (PMID 38777879, 2024). "As shown in an imiquimod-induced setting, both RNA and DNA sensing pathways may be activated in a TLR7-induced way without viral infection, indicating that other environmental stimuli such as chemicals can induce activation of cellular pathways involved in SLE." (PMID 38791389, 2024). "Furthermore, TLR7−/− mice clear acute LCMV-ARM infection, but not the chronic LCMV-CL13, indicating that TLR7 may play different roles in acute versus chronic viral infection." (PMID 33331816, 2021). "Indeed, we and others have shown that viruses hijack the endocytic compartment to drive a TLR7‐dependent NOX2 oxidase‐dependent ROS process that suppresses Type I IFN responses, which is one of the most important antiviral mechanisms that enable the immune system to clear a viral infection." (PMID 30884042, 2019). "Therefore, to mechanistically delineate the contribution of macrophages to CCL2 production during viral infection, monocyte-derived macrophages were stimulated with purified viral PAMPS, poly I:C, a TLR3 agonist, and ssRNA40, which is derived from the HIV-1 long terminal repeat and activates TLR7/8." (PMID 29466439, 2018). "Thus, pDCs have the unique ability to detect viral infections without the requirement of endogenous viral replication, because they must be able to take up oligonucleotides from viruses or infected cells into specialized endosomes for TLR7 or 9 triggering." (PMID 21994554, 2009).